LINC00840 (long independently transcribed non-coding RNA 840)
Synonyms: C10orf136; bA168P8.1; LINC00619
Gene: Long non-coding RNA gene on chromosome 10 (43,778,946 to 43,901,405, forward strand). Ensembl gene ENSG00000226808.
Diseases named in the same sentence as LINC00840 in open-access papers:
LINC00840 is named in the same sentence as 1 disease in open-access papers, as found by Europe PMC text mining. Sharing a sentence is not in itself a finding about the gene and the disease.
LINC00840 shares sentences with these, for which no sentence is quoted: osteosarcoma (1 paper).